HIF1A (hypoxia inducible factor 1 subunit alpha)
Diseases named in the same sentence as HIF1A in open-access papers (continued):
Sharing a sentence is not in itself a finding about the gene and the disease.
osteoporosis (continued). "Matrix metalloproteinase (MMP)-2 inhibitor 1 induces osteogenesis differentiation of bone marrow mesenchymal stem cells (BMSCs) and promotes type H vessel angiogenesis to rescue osteoporosis through the HIF-1α signaling pathway." (PMID 40025573, 2025). "We then found that, in a male osteoporosis model in which bilateral testes were removed (orchiectomy, ORX), the administration of our HIF1α inhibitor completely blocked bone loss in ORX mice as well." (PMID 40004668, 2025). "This study is the first to identify that 2′′-O-RhamnosylIcariside II can treat osteoporosis by specifically targeting and inhibiting HIF1-α in osteoblasts." (PMID 38931373, 2024). "It achieves these effects by reducing marrow adipose tissue in the femur, protecting osteoblast embedded in the compact bone, and inhibiting HIF-1α protein expression, thereby exerting anti-osteoporosis effects." (PMID 38931373, 2024). "Subsequent network analysis and analysis of the literature selected six potential active compounds as the representative bioactive compounds of Epimedium, and HIF-1α as their potential target protein in treating osteoporosis." (PMID 38931373, 2024). "Further experiments are needed to confirm the potential therapeutic effects of 2′′-O-RhamnosylIcariside II on osteoporosis by regulating HIF-1α." (PMID 38931373, 2024). "This study is the first to describe the therapeutic effects of 2-O-RhamnosylIcariside II on osteoporosis, which was done, specifically, through a mechanism that targets and inhibits HIF-1α." (PMID 38931373, 2024). "The HIF-1α signaling pathway comprises 38 potential target proteins, of which 13 have been identified as targets for osteoporosis." (PMID 38931373, 2024). "This stress leads to increased expression of Hif1α, a factor known for promoting adverse effects in multiple organs, including angiogenesis in retina and white adipose tissue, and osteoporosis." (PMID 38923793, 2024). "Many studies have shown that inhibition of HIF-1α can reduce osteoclast activity, thereby exerting an anti-osteoporosis effect." (PMID 38931373, 2024). "Collectively, these data demonstrate that HIF-1α directly binds to the Rankl promoter and regulates RANKL expression in bone marrow B cells during estrogen deficiency-induced osteoporosis." (PMID 35177582, 2022). "On the other hand, there is the finding that the OVX rats, which have an osteoporosis-like performance, have a higher level of HIF-1α." (PMID 36080305, 2022). "We also investigated the relevance of hypoxia to HIF-1α protein stabilization within the osteoporotic bone marrow niche during OVX-induced osteoporosis." (PMID 35177582, 2022). "All these data suggest that activation of HIF-1α signaling in B cells enhances osteoclastogenesis and accelerates osteoporosis." (PMID 35177582, 2022). "To explore the molecular mechanism involved in abnormal activation of HIF-1α signaling during OVX-induced osteoporosis, we dissected the transcriptional network in total bone marrow B cells treated with estrogen (1 μmol·L−1) or vehicle by RNA-seq." (PMID 35177582, 2022). "Meanwhile, HIF-1α played an important role in hypoxia-induced osteoporosis and was directly involved in the regulation of bone homeostasis, which was a potential target for the treatment of osteoporosis in respiratory patients." (PMID 35903070, 2022). "The activation of hypoxia-inducible factor 1α (HIF-1α) signaling has promising implications for the treatment of bone diseases such as osteoporosis and skeletal fractures." (PMID 35118061, 2021). "Combined with previous experimental results, it is likely that ERβ has a major impact on angiogenesis in osteoporosis under the hypoxia condition induced by HIF-1a." (PMID 31355247, 2019). "Under sex hormone-depleted conditions, Hif1α was demonstrated to be a therapeutic target in conditions of post-menopausal and male osteoporosis." (PMID 27802325, 2016).
osteoporosis (continued). "We have also shown that eldecalcitol, a vitamin D analogue and inhibitor of bone resorption in osteoporosis patients, functions as a Hif1α inhibitor." (PMID 27802325, 2016). "Eldecalcitol, which is used to inhibit bone resorption in osteoporosis patients, lowers Hif1α protein levels in osteoclasts, comparable to our observation following SERM treatment." (PMID 27802325, 2016). "Targeting of HIF-1α by zoledronic acid, a drug previously used in the prevention or treatment osteoporosis, has the potential to reverse or prevent anti-estrogen resistance in vitro and in vivo." (PMID 25929338, 2015). "Recently, HIF1α expression in osteoclasts was demonstrated to be required for development of post-menopausal osteoporosis." (PMID 25375896, 2014). "Other factors such as Yes-associated protein 1 (YAP1)/Transcriptional activator with PDZ domain (TAZ) or hypoxia-inducible factor 1α (HIF1α), reported to affect type H vessel formation, may also be potential targets for preventing and treating osteoporosis." (PMID 40159493, 2025). "In mice genetically engineered to lack HIF1α in osteoclasts, no bone loss occurs in a postmenopausal osteoporosis model (ovariectomy, OVX) in which both ovaries are removed." (PMID 40004668, 2025). "We hypothesized that metformin ameliorates osteoporosis by enhancing HIF1α signaling-induced bone angiogenesis via inhibiting YAP1/TAZ expression." (PMID 40159493, 2025). "Therefore, we infer that HIF-1α is a promising target protein of the active compounds in Epimedium for the treatment of osteoporosis." (PMID 38931373, 2024). "Therefore, 2′′-O-RhamnosylIcariside II can treat osteoporosis in vivo by inhibiting the expression of the HIF-1α protein in the femoral bone." (PMID 38931373, 2024). "Therefore, the HIF-1α signaling pathway is very likely the pathway regulated by Epimedium in exerting its anti-osteoporosis effects." (PMID 38931373, 2024). "Therefore, in this study, we focused on investigating the osteoporosis treatment effects of 2′′-O-RhamnosylIcariside II by targeting HIF-1α in osteoblasts." (PMID 38931373, 2024). "Furthermore, this research contributes new evidence supporting HIF1-α as a viable therapeutic target for osteoporosis." (PMID 38931373, 2024). "It was reported that HIF-1α could alleviate osteoporosis by regulating osteoclast and osteoblast differentiation, with its inhibition shown to reduce osteoclast activity." (PMID 38931373, 2024). "Gushukang, a traditional herbal compound used in Chinese medicine for the treatment of osteoporosis, could also induce type H vessel formation via elevated HIF‐1α expression in mice." (PMID 38353470, 2024). "Therefore, we aimed to explore the potential osteoporosis treatment of 2′′-O-RhamnosylIcariside II targeting HIF-1α in osteoblasts." (PMID 38931373, 2024). "It was also reported that Isoquercetin could improve the histological characteristics of OVX-induced osteoporosis by inhibiting HIF-1α and increasing β-catenin expression, which is biomarker of osteoblast differentiation." (PMID 38931373, 2024). "Ferroptosis induced by targeting HIF1A in osteoclasts may be a new method for the treatment of osteoporosis." (PMID 37144125, 2023). "The data implied that CIHH relieved the SCI-induced osteoporosis might be at least partly mediated by the HIF-1α signaling pathway." (PMID 37229453, 2023). "The study aimed at revealing the unknown role of HIF1α in aged bone, thus broadening its practical application in senile osteoporosis." (PMID 35123567, 2022). "Among them, HIF-1a and VEGFA may be the key target proteins for which MQEP exerts its anti-osteoporosis and bone loss effects." (PMID 36147560, 2022). "After treatment with drugs, the osteoporosis was alleviated and the level of HIF-1α decreased." (PMID 36080305, 2022). "New awareness about HIF1α will be conducive to its future application in senile osteoporosis." (PMID 35123567, 2022).
osteoporosis (continued). "Therefore, the role of HIF-1α in osteoporosis, especially in high-altitude osteoporosis, remains controversial and unclear." (PMID 36080305, 2022). "The Hif1a-specific inhibitor 2ME2 can prevent osteoporosis in OVX mice, and the induction of ferroptosis by targeting Hif1a in osteoclasts may be a novel approach for the treatment of osteoporosis." (PMID 36093072, 2022). "For treatment, intermittent hypoxic therapy could activate the adaptive process of hypoxia mediated by HIF-1α, which was helpful for the treatment of hypoxia-induced osteoporosis." (PMID 35903070, 2022). "HIF-1α was a necessary factor-mediated hypoxia-induced osteoporosis." (PMID 35903070, 2022). "In this way, a comprehensive conception of HIF1α-regulated aging-related bone metabolism would be constructed, and practical applications of HIF1α in senile osteoporosis could be promoted." (PMID 35123567, 2022). "Similarly, miR-497~195 cluster improves senile osteoporosis by inducing Type H vessel angiogenesis coupling with osteogenesis via Notch and HIF-1α pathways." (PMID 36428981, 2022). "Furthermore, activation of the HIF-1α pathway using hypoxia-mimicking agents such as deferoxamine and dimethyloxalylglycine is a promising treatment for bone diseases such as osteoporosis and skeletal fractures." (PMID 35118061, 2021). "In addition, it suppresses the protein hypoxia-inducible factor 1 alpha (HIF1-α) in osteoclasts responsible for developing osteoporosis, similarly to estrogen." (PMID 29160416, 2017). "We previously demonstrated that Hif1α could be a therapeutic target in osteoporosis, leading us to test the effects of candidate anti-bone resorptive agents on Hif1α protein suppression in osteoclasts in vitro." (PMID 27802325, 2016). "IHC analysis showed that HIF-1α expression was significantly increased in the residual specimen after letrozole treatment, while after zoledronic acid treatment due to severe osteoporosis, the expression of HIF-1α and the Ki-67 index was significantly decreased." (PMID 25929338, 2015). "Nonetheless, HIF1α inhibition could serve as an index to assess osteoclastogenesis in vitro when developing anti-osteoporosis agents." (PMID 25375896, 2014). "Additionally, it provides new evidence supporting HIF-1α as a therapeutic target for osteoporosis." (PMID 38931373, 2024). "Furthermore, it offers fresh evidence supporting HIF-1α as a therapeutic target for osteoporosis." (PMID 38931373, 2024). "Thus, we preferred that CIHH protected against SCI-induced osteoporosis might be at least partly mediated by the upregulation of HIF-1α signaling pathway." (PMID 37229453, 2023). "Additionally, HIF-1α was a potential target for the treatment of osteoporosis in respiratory patients, which could be activated under hypoxia condition and involved in the process of bone remodeling." (PMID 35903070, 2022). "Therefore, our findings suggest that the HSP70/HIF-1α axis may offer a novel therapeutic strategy for osteoporosis." (PMID 35177582, 2022). "In addition, matrix metalloproteinase-2 inhibitor 1 (MMP2-I1) could induce BMSCs osteogenesis differentiation and promote Type H vessel angiogenesis through the HIF-1α signal pathway, rescuing osteonecrosis, bone defect, as well as osteoporosis." (PMID 36428981, 2022). "The previous quantitative analysis of the aqueous decoction extract of MQEP revealed that Isopsoralen is the main component of MQEP, HIF-1a and VEGF may be the key protein on which MQEP exerts its anti-osteoporosis and bone loss effects by promoting angiogenesis." (PMID 36147560, 2022). "It improves bone homeostasis by regulating the AMPK/mTOR and HIF-1α/VEGF signal pathways, preventing and treating glucocorticoid-induced osteoporosis." (PMID 36428981, 2022). "In conclusion, HIF-1α signaling in B cells is crucial for the control of osteoclastogenesis, and the HSP70/HIF-1α axis may serve as a new therapeutic target for osteoporosis." (PMID 35177582, 2022).
osteoporosis (continued). "Finally, the hypothesis that osteoblast HIF-1α pathway regulates osteoclastogenesis via IL-33-miR-34a-5p-Notch1 still needs to be confirmed in animal models of osteoporosis, and the clinical relevance of this pathway in osteoporosis or osteopetrosis remains to be elucidated." (PMID 29085370, 2017). "Thus, suppression of HIF1α protein activity in osteoclasts in vitro, which is more efficiently achieved by ED71 rather than by 1,25(OH)2D3, could be a reliable read-out in either developing or screening reagents targeting osteoporosis." (PMID 25375896, 2014).
Arthritis (38 papers, 2010 to 2025). Inflammation of a joint. "Altogether, these data indicate that loss of HIF-1α in B cells exacerbates arthritis development likely by impairing the IL-10 production by B cells." (PMID 29343683, 2018). "The loss of HIF-1α in macrophages and neutrophils reduces the severity of cutaneous inflammation and passive arthritis models, and HIF-1α deficient DCs were shown to have decreased expression of co-stimulatory markers compared to wildtype DCs and a reduced capacity to induce T cell proliferation." (PMID 33382742, 2020). "The chemotherapeutic agent Taxol, known to inhibit HIF‐1α production, has been demonstrated to mitigate collagen‐induced arthritis through modulation of the HIF‐1α/VEGF/ANG‐1 axis." (PMID 40170391, 2025). "HIF-1α stabilization in synovial Th cells under hypoxia promotes pathogenic Th17 survival; HIF-1α inhibition is therapeutic in experimental arthritis." (PMID 41476956, 2025). "In AIDs, downregulation of HIF-1α significantly diminishes the number of IL-10-secreting B cells, exacerbating collagen-induced arthritis and EAE." (PMID 39575238, 2024). "Considering these findings, we wonder if SDSS exerts anti-arthritis properties by inhibiting HIF-1α/STAT3/NLRP3 axis." (PMID 36838542, 2023). "This is the first in vivo and in vitro evidence that SDSS exerts its role in ameliorating arthritis through suppressing the HIF-1α/STAT3/NLRP3 pathway, therefore modulating the inflammatory activation in macrophages." (PMID 36838542, 2023). "During the arthritis, boosted the level of HIF1α and ANG-1, a similar result wasobtained in the CFA group rats." (PMID 32945205, 2020). "HIF-1α drives IL-10 expression in B-cells in controlling autoimmune inflammation such as arthritis and experimental autoimmune encephalomyelitis." (PMID 33519819, 2020). "Significant, positive correlations were observed between VEGF mRNA and extent of paw swelling, between HIF-1α protein and the arthritis index, while VEGF mRNA and HIF-1α protein were positively correlated with CD34." (PMID 29996499, 2018). "Conditional knock-out of HIF-1α in animal models of RA demonstrated clinical and histological improvement of experimental arthritis." (PMID 27445820, 2016). "Ets-1 is inducible by hypoxia and co-localizes with HIF-1α in the synovial inflammatory infiltrate in an adjuvant-induced arthritis model in rats." (PMID 27549205, 2016). "In a rat arthritis model, synovial angiogenesis was associated with overexpression of VEGF, CD34, and HIF-1α, and the levels of HIF-1α were positively correlated with the arthritis index." (PMID 27549205, 2016). "Administration of C-AR (50 mg/kg) and HIF-1α inhibitor digoxin (100 μg/kg) reduced swollen ratio and ameliorated the clinical symptoms indicated the reduced arthritis index scores." (PMID 28003810, 2016). "While the expected increase in HIF-1α occurred during arthritis development, HT significantly reduced the HIF-1α up-regulation." (PMID 25793532, 2015). "CIHH pretreatment has a protective effect against collagen-induced arthritis in rat through down-regulation of HIF-1α and NF-κB, inhibition of inflammatory cytokines TNF-α and IL-17, and balance in CD4/CD8 and Th1/Th2 T lymphocytes." (PMID 25861246, 2015). "Our results in experimental arthritis in mice indicated that NO promoted angiogenesis by activating HIF-1α and VEGF and in turn mitigated glycolysis after enhanced angiogenesis." (PMID 22479635, 2012). "The present study has been designed to use the adjuvant-induced arthritis model to examine the effects of HA on the changes of immunohistochemical expressions of HIF-1α, iNOS, and MMP3 in the synovial tissues in the early phase of arthritic inflammation." (PMID 21679445, 2011). "Recently new small molecular drugs that have inhibitory effect on HIF-1α have been tested in arthritis models." (PMID 20353560, 2010).